NF1 (neurofibromin 1)
Diseases named in the same sentence as NF1 in open-access papers (continued):
Sharing a sentence is not in itself a finding about the gene and the disease.
Cognitive impairment (continued). "Heat-shock induced neurofibromin was expressed in adult NF1-/- fruit flies, rescuing the learning deficits, indicating that developmental factors are not causing the cognitive deficits." (PMID 16524466, 2006). "The biological mechanisms by which NF1 gene mutations lead to such cognitive deficits are not well understood, although excessive Ras signaling and increased GABA mediated inhibition have been implicated." (PMID 16524466, 2006). "We could speculate that this pattern of more pronounced IS behaviours, which have been conceptualised as ‘higher-order’ RRBs, may relate to the relatively higher and truncated IQ in NF1, as compared to the greater prevalence of severe intellectual impairments in idiopathic autism." (PMID 34983638, 2022). "It is debatable if patients with MNF1 should be clinically examined and undergo follow-up in accordance with the standard NF1 guidelines, as MNF1 patients more often may develop more benign phenotypes and thereby less disease-associated complications including cognitive impairment." (PMID 33853649, 2021). "Through the analysis on a well-described cohort of 135 individuals (including 90 individuals ≥9 years) we bring to attention the significant risk for cognitive impairment, learning disabilities, and nonoptic brain tumors associated with this particular NF1 genotype." (PMID 30190611, 2019). "Furthermore, aberrant activation of mTORC1 signaling is a common feature in syndromes associated with autistic phenotypes and cognitive impairments such as TSC, fragile-X, neurofibromatosis-1 (NF1) as well as those with PTEN mutations seen in ASD with macrocephaly." (PMID 23514105, 2013). "Treatment with the HCN channel agonist lamotrigine during adulthood rescued the cognitive deficits in two different Nf1 mouse models, thereby establishing an important function of HCN channels in mediating the NF1 phenotype." (PMID 28455524, 2017). "Both NF1 and VCP/p97 are critical for dendritic spine formation, which provides the cellular mechanism explaining the cognitive deficits and dementia found in patients." (PMID 22449146, 2012). "In the current study, no statistical difference for prevalence of cognitive impairment between individuals carrying the NF1 deep intronic PVs flanking exon 31 and the remaining NF1-affected individuals was observed (5/17 vs. 40/134, P = 1.0 with Fisher’s exact test)." (PMID 37186028, 2023). "Overall therefore, TS, NF1 and NS might be regarded as behavioural models of specific subtypes, or symptoms, of ADHD in the absence of general cognitive impairments." (PMID 28694877, 2017).
brain tumors (63 papers, 2008 to 2026). "Several critical genes in the MAPK signaling pathway, including BRAF, FGFR, and NF1, are mutated in brain tumors." (PMID 41323387, 2025). "The NF1 tumor predisposing syndrome increases the risk of developing brain tumors, which are observed in approximately 15–20% of NF1 cases." (PMID 38874808, 2024). "Due to the major differences between the NF1 and non-NF1 brain tumours regarding natural history, prognosis, underlying molecular mechanisms and disease manifestation there are currently no NF1-specific treatments for HGGs." (PMID 36684394, 2023). "Lymphoproliferative malignancies associated with NF1 are limited, although the most common are brain tumors." (PMID 36557032, 2022). "NF1 also predisposes to a wide spectrum of malignancies, of which MPNSTs and brain tumors are the most represented." (PMID 34199217, 2021). "Relevant to brain tumors, NF1 patients with 5′ NF1 gene mutations have higher chance developing optic gliomas compared to patients with mutations at other locations of the NF1 gene." (PMID 28066715, 2016). "To evaluate the therapeutic potential of Neurofibromin 1 (NF1)-derived SAAVs - given that NF1 is frequently mutated in malignant brain tumors - we prioritized the 40 NF1 SAAVs determined to be HLA-A*02:01 binders using computational prediction coupled with experimental validation." (PMID 42146370, 2026). "Children with NF1 are prone to the development of multiple nervous system abnormalities, including autism and brain tumors, which could reflect the effect of NF1 mutation on microglia function." (PMID 37990867, 2023). "NF1-associated GH excess should be considered in patients with characteristic clinical signs and symptoms of dermal neurofibromas, café-au-lait spots, axillary or inguinal freckling and hamartomas of the iris as well as brain neoplasms due to inactivating mutation of NF1 gene." (PMID 33543431, 2021). "In terms of cancer biology, although ventrally derived OPCs diminished at an older age during normal development, they still could break this limit and function as a cell origin of brain tumors after acquiring certain oncogenic mutations, such as NF1 deficiency." (PMID 34396711, 2021). "Second, the finding that the immune circuits required for Nf1-OPG formation and progression can serve as convergence points for brain tumor risk factors provides a contextual framework for understanding cancer at a circuit level." (PMID 38308315, 2024). "Previously, we have shown that heterozygous Nf1-mutant murine microglia make key contributions to low-grade brain tumor (glioma) pathogenesis." (PMID 37990867, 2023).
brain tumors (continued). "About 15–20% of individuals with NF1 develop brain tumors and one third of these occur outside of the optic pathway." (PMID 36730269, 2023). "Neurofibromatosis 1 (NF1) is a disease with clinical heterogeneity where affected individuals show a wide variety of pathologies, including brain tumours to developmental abnormalities." (PMID 35382567, 2022). "The most common brain tumor affecting individuals with NF1 is the OPG seen in 15 to 20% of children with NF1." (PMID 32014052, 2020). "NF1 symptoms were mentioned in several members of the family, including their respective parents (patients II-3 and II-2), an aunt who died from a brain tumor (II-1), and her daughter (III-1)." (PMID 31443423, 2019). "Using the betweenness centrality measure, we identified Etv5 as a potential tissue-level regulator in murine neurofibromatosis type 1 (Nf1) low-grade brain tumors (optic gliomas)." (PMID 29787563, 2018). "Our proof-of-principle study uses complexity analysis of weighted transcription networks to identify transcription factors that comprise a regulatory network unique to low-grade brain tumors arising in the optic nerves of Nf1 mutant mice (optic gliomas)." (PMID 29787563, 2018). "The second group of children with PA includes those who harbor a germline mutation in the Neurofibromin (NF1) tumor suppressor gene and, therefore, have NF1 as the genetic etiology for their brain tumors." (PMID 28066715, 2016). "Pilocytic astrocytoma is also the most frequent brain tumor arising in the setting of NF1, another genetic syndrome resulting in constitutive MAPK/ERK pathway activation." (PMID 22011734, 2011). "We thus combined SNP and qPCR data, and further determined the incidence of 7q34 duplication based on histology, for example, sporadic JPA (N=53), NF1-associated JPA (N=4), diffuse astrocytomas (N=27) and the other paediatric brain tumours (N=31)." (PMID 19603027, 2009). "Therefore, a DL model is pre-trained on data that is more similar to the target dataset and then fine-tuned on the target dataset, followed by final training with NF1 brain tumor samples." (PMID 41168866, 2025). "More than 60 results are related to NF1, and over 170 are related to brain tumors." (PMID 41168866, 2025). "Despite the fact that the loss of NF-1 function is related to resistance to targeted therapies, MEK inhibitors may be effective against NF-1-mutated brain tumors." (PMID 35875139, 2022). "A publication assessing prognostic factors for NF1 patients with brain tumours found that having multiple tumours is not a risk factor for death; however, it did not distinguish between optic and non-optic tumours." (PMID 28202035, 2017). "Currently, there are several registries for brain tumors and others, specifically for NF1." (PMID 28066715, 2016). "In our institution, a total of 12 children with NF1 and OPG underwent radiation therapy over the last 31 years, 11 of them irradiated before 2000, when our brain tumor program was initiated." (PMID 35592129, 2022). "Although rare, NF1 is one of the most common genetic disorders in humans, and PAs, when included in the LGG category, are the most common pediatric brain tumors." (PMID 28066715, 2016).
brain tumors (continued). "UBOs are non-enhancing T2 hyperintensities typical of NF1 found in the brain and medulla, which are described as potential precursors of brain tumors." (PMID 32486389, 2020). "Interestingly, most genetic alterations harbored by brain tumors including alterations of EGFR, NF1, PTEN and AKT, are known to be involved in autophagy regulation." (PMID 29692710, 2018). "Mice heterozygous for Nf1 (Nf1+/− mice) or lacking Nf1 expression in astroglial cells alone (GFAPCre; Nf1flox/flox mice) do not develop brain tumors." (PMID 25008045, 2014). "Moore and colleagues evaluated the effects of NF1 with and without a codiagnosis of a brain tumor." (PMID 31717965, 2019). "Indeed, it was identified in 35 of 53 (66%) JPA, and was absent in NF1-associated JPA and the other brain tumours." (PMID 19603027, 2009). "Finally, within the NF1 literature, children with diagnosed or treated OPG have typically been excluded from neuropsychology studies, whereas the very few studies that attempted to disentangle the relative contribution of NF1 and brain tumour did not always focus on OPG20–22." (PMID 32094393, 2020).
pilocytic astrocytoma (62 papers, 2009 to 2025). Pilocytic astrocytoma is a rare subtype of low-grade glioma of the central nervous system characterized by a well circumscribed, often cystic, brain tumor with a discrete mural nodule and long, hair-like projections that extend from the neoplastic astrocytes. "This included patients with non-NF1 pilocytic astrocytoma with KIAA1549::BRAF or BRAF p.V600E mutation (stratum 1), NF1-associated pLGGs (stratum 3) and those with recurrent/progressive non-NF1 optic pathway and hypothalamic pLGGs (stratum 4)." (PMID 40422539, 2025). "It was noteworthy, nevertheless, that NF1-associated pilocytic astrocytoma evinced a better prognosis in children than sporadic pilocytic astrocytoma." (PMID 38281032, 2024). "Since NF1-associated tumors can present with pronounced pleomorphic nuclei, and the MC aligned with PA with a CS of 0.98, the final diagnosis leaned towards pilocytic astrocytoma, NF1-associated." (PMID 37998600, 2023). "The sensitivity of the PXA methylation class is underscored, urging caution when confronting a differing methylation class and prompting consideration of new differential diagnoses like HGAP, HPAP, pilocytic astrocytoma NF1-associated, and NET-PATZ1." (PMID 37998600, 2023). "When there is a misalignment between PXA’s morphological diagnosis and its methylation class, it is imperative to factor in newly identified differential diagnosis entities such as HGAP, HPAP, NF1-associated pilocytic astrocytoma, and NET-PATZ1." (PMID 37998600, 2023). "The deficiency of 1 NF1 allele was recognized in 11 of 12 (92%) instructive NF1‐related pilocytic astrocytoma." (PMID 37675821, 2023). "As the available clinical information does not include specific information about the patients’ genetic alterations, the difference in GFAP staining in NF1-associated versus non-NF1-associated pilocytic astrocytomas cannot be assessed." (PMID 35885538, 2022). "A previously detected truncating germline mutation in NF1 in a patient with pilocytic astrocytoma (P2806), was paired with a novel somatic NF1 truncating indel and confirmed a clinical diagnosis of neurofibromatosis type 1 (NF1)." (PMID 35449451, 2022). "A very recent report demonstrated promising results of LITT for two pediatric NF-1- associated, chemo-resistant, G1 pilocytic astrocytomas." (PMID 36230704, 2022). "The majority of non NF1-associated pilocytic astrocytoma carries an activation of BRAF due to fusion of BRAF with KIAA1549." (PMID 31906320, 2020). "It is important to underline that Neurofibromatosis type I (NF1) loss is a common autosomal dominant tumor predisposition syndrome: approximately 15 to 20% of children with NF1 loss develop pilocytic astrocytomas." (PMID 30279357, 2018). "Of note, the MATN2 protein is elevated in NF1-associated pilocytic astrocytoma with an unusually aggressive clinical phenotype; it will therefore be interesting to further examine the effects of MATN2 and potential regulation by miR-124 and miR-153 in SEPN." (PMID 29383182, 2017). "Neurofibromatosis type 1 (NF1) is an autosomal dominant disorder that results from germline mutations of the NF1 gene, creating a predisposition to low-grade gliomas (LGGs; pilocytic astrocytoma) in young children." (PMID 28066715, 2016). "While the association between NF-1 and cancer is well documented in the literature, there is some controversy surrounding the importance of NF-1 in the tumorigenesis of spontaneous pilocytic astrocytomas." (PMID 26525348, 2015). "There is limited data on methylation changes, but methylation of NF1 was recently found to be the cause of a somatic second-hit inactivation in pilocytic astrocytoma from a patient with NF1." (PMID 25026295, 2014). "The morphological and NGS reevaluation of the initial resection could have pointed to either pilocytic astrocytoma with an NF1 mutation or PXA." (PMID 37998600, 2023).
pilocytic astrocytoma (continued). "In addition, NGS cannot detect methylation defects that have been demonstrated to inactivate the NF1 gene in NF1-associated pilocytic astrocytoma." (PMID 29673180, 2018). "Sporadic pilocytic astrocytomas, in contrast, rarely demonstrate allelic loss at the NF1 locus." (PMID 19333441, 2009). "Most previously reported cases have involved pilocytic astrocytomas (WHO grade 1), particularly in association with neurofibromatosis type 1 NF1, or in tumors located within the optic pathways, thalamus, or pediatric brainstem." (PMID 41393573, 2025). "Notable mutations driving these tumours include the KIAA1549‐BRAF fusion, which is common in pilocytic astrocytoma (approximately 70%) and rosette‐forming glioneural tumours (around 30%) in non‐NF1 cases." (PMID 40735832, 2025). "Two of the NF1 cases had a remote history of an ependymoma or a pilocytic astrocytoma at sites distant from the HGAP tumor." (PMID 41239912, 2025). "On the contrary, only 1 of 24 educational (4%) irregular pilocytic astrocytoma showed allelic misfortune in the NF1 district." (PMID 37675821, 2023). "Using the Conditionally Reprogramming Culture (CRC) technique, we previously developed a human pilocytic astrocytoma cell line derived from a patient with NF1." (PMID 35740680, 2022). "Grade 1 pilocytic astrocytomas of the optic pathway, also known as optic pathway gliomas (OPGs), are the second most common tumor in NF1, and are also driven by increased RAS-dependent signaling." (PMID 35188187, 2022). "The first occurs primarily during childhood, harbors biallelic NF1 inactivation only, follows a more indolent clinical course, and has a unique epigenetic signature for which we propose the terminology “pilocytic astrocytoma, arising in the setting of NF1”." (PMID 35945463, 2022). "In the rare phenomenon of pilocytic astrocytomas with anaplasia, ATRX loss frequently co-occurs with NF1 loss, as well as mutually exclusive alterations in the members of the MAPK pathway (e.g. BRAF)." (PMID 31462295, 2019). "We further validated the differential expression of Etv5 and its target genes in several other murine models of Nf1 optic glioma, as well as in human pilocytic astrocytomas." (PMID 29787563, 2018). "Some researchers have shown that total NF1 transcript levels are high in pilocytic astrocytomas and that the NF1 type I and type II expression ratios in pilocytic astrocytomas are similar to ratios in normal brain tissues and HGGs." (PMID 26525348, 2015). "In this setting, pilocytic astrocytomas are typically located in the optic nerve, often bilaterally, and carry allelic losses at the NF1 tumor suppressor gene locus at 17q11.2." (PMID 19333441, 2009). "The only mortality was a female NF1 patient with a medulla oblongata pilocytic astrocytoma." (PMID 39145885, 2024). "First, leveraging human bulk RNA sequencing data, we identified PDPN as a gene differentially expressed both in NF1-associated and sporadic pilocytic astrocytomas relative to control non-neoplastic brain tissue." (PMID 35986378, 2022). "The first harbored biallelic NF1 inactivation only, occurred primarily during childhood, followed a more indolent clinical course, and had a unique epigenetic signature for which we propose the terminology “pilocytic astrocytoma, arising in the setting of NF1”." (PMID 35945463, 2022). "Finally, we validated the differential expression of Etv5 in several other Nf1 murine models of optic glioma, as well as in human low-grade glioma (pilocytic astrocytoma, PA) datasets." (PMID 29787563, 2018). "Furthermore, all pilocytic astrocytomas in the study’s cohort harbored a MAPK pathway alteration, and Genome MuSiC algorithm suggested that the BRAF, FGFR1, KRAS, and NF1 were the only genes found to be most significantly mutated." (PMID 26525348, 2015).